AMH (anti-Mullerian hormone)
Diseases named in the same sentence as AMH in open-access papers (continued):
Sharing a sentence is not in itself a finding about the gene and the disease.
endometriosis (continued). "These correlations remained significant even after adjustment for endometriosis, age, smoking habits, BMI, IVF-ET/ICSI, FSH, LH, estradiol, AMH, and the duration of infertility, confirming that systemic oxidative stress reflects FF oxidative stress." (PMID 29462946, 2018). "The group withnormal AMH levels included mainly ovulatory women with other IVF/ICSI indicationssuch as male factor, tubal factor or unexplained infertility, and endometriosis, asdescribed by other authors (Gomez etal., 2015)." (PMID 28050957, 2016). "AMH and AMH RII isoforms, as well as cytochrome P450, were expressed in both endometriosis epithelial and stromal cells." (PMID 24886254, 2014). "Anti-Müllerian hormone (AMH) levels, the antral follicle count (AFC), the number of retrieved oocytes as well as the rate of mature oocytes and the fertilization rate were compared among the different subtypes of endometriosis." (PMID 42270946, 2026). "Compared to healthy women, patients with endometriosis had lower AMH and sinus follicle counts, especially in patients with endometriosis (III and IV), with a more significant decrease in AMH levels and a reduced number of oocytes and transferable embryos obtained." (PMID 37560165, 2023). "Up to now, few studies have been interested in comparing IL-6 and AMH levels in women with or without endometriosis." (PMID 36902616, 2023). "A recent matched-cohort study, matching women with endometriosis with those without, of similar age, type of stimulation and AMH (anti-mullerian hormone) levels, also reported similar LBR and clinical pregnancy rates." (PMID 37123402, 2023). "Reduction rates in the RAL group were smaller than those in the SPA laparoscopy group for patients with mild endometriosis (early stage, AAGL stage I/II) (AMH reduction rates at 3 months postoperative: RAL vs. SPA laparoscopy, 23.58 ± 14.98% vs. 33.51 ± 19.98%; p = 0.04)." (PMID 37510787, 2023). "The aim of this study was to compare follicular liquid levels of IL6 and AMH in women with and without endometriosis and to evaluate their potential effect on ICSI outcomes." (PMID 36902616, 2023). "Recent studies have reported that endometriosis surgery has a negative impact on ovarian reserve, as shown in post-operative follow-up of AMH and antral follicles." (PMID 34755503, 2022). "Regarding the endometriosis patients treated prior to IVF, the predictors of pregnancy achievement were basal serum levels of P4 (p = 0.042); FSH (p = 0.017), LH (p = 0.038), and AMH levels (p = 0.006); and the use of the long stimulation protocol (p = 0.034)." (PMID 36294778, 2022). "It was observed that the AMH level, without surgical treatment, was lower in group A (women with endometriosis) than in group B, particularly in the subgroup with ovarian endometriomas." (PMID 36120472, 2022). "Women with endometriosis treated with ovarian surgery demonstrate an especially steep decline in AMH levels, but women with endometriosis who do not undergo surgery also show accelerated declines in AMH levels relative to unaffected women." (PMID 34295358, 2021). "In this present study, we found a significant correlation between serum AMH and AMH in PF in both women with endometriosis and control women without disease." (PMID 33263001, 2020). "Serum AMH levels were inversely and significantly correlated with age in women with endometriosis (R2 = 0.092, P = 0.004) and in control women without statistical significance (R2 = 0.078, P = 0.12)." (PMID 33263001, 2020). "Similar to our study, this study also showed a significant linear correlation between AMH in peritoneal fluids and in serum in both women with endometriosis and control women without disease." (PMID 33263001, 2020). "In this study, we found that MnBP affected cell health, AMH, and inhibin B production, while these cells were not collected from women with endometriosis and the control groups." (PMID 32151056, 2020).
endometriosis (continued). "AMH levels in PF were also inversely but not significantly correlated with age in women with and without endometriosis (R2 = 0.029, P = 0.11 and R2 = 0.027, P = 0.37, respectively)." (PMID 33263001, 2020). "AMH levels in PF and their correlation with serum AMH levels in women with and without endometriosis had been reported previously." (PMID 33263001, 2020). "The trends of linear correlations between age and AMH in PF in women with and without endometriosis were also reported in the previous study, which correspond with our present findings." (PMID 33263001, 2020). "Studies show that patients with moderate or severe endometriosis without previous surgeries have lower levels of Anti-Mullerian Hormone (AMH) than healthy women." (PMID 32660473, 2020). "In this study, we investigated the levels of AMH in peritoneal fluids (PF) in women with and without endometriosis." (PMID 33263001, 2020). "Peritoneal endometriosis expresses AMHR2, the specific receptor for AMH, which may implicate a functional role of AMH in growth maintenance of these lesions." (PMID 33263001, 2020). "In this study, we investigated the levels of AMH in PF in women with and without endometriosis and compared them according to the age of the subjects and the presence of disease." (PMID 33263001, 2020). "Interestingly, the results of the statistical analyses indicate that this correlation remained significant even after adjustment for endometriosis, age, smoking habits, BMI, IVF-ET/ICSI, FSH, LH, estradiol, AMH, and duration of infertility." (PMID 29462946, 2018). "A reduction in the level of AMH, obtained oocytes, metaphase II oocytes and transferable embryos in patients with moderate to severe endometriosis represents a negative impact of endometriosis on in vitro fertilization and fertility in these patients." (PMID 30775688, 2018). "In fact, in the same AMH level, the presence or absence of endometriosis did not impressed ovarian response and endometrial receptivity." (PMID 30775688, 2018). "In support of this, in this study when the AMH level was normal, ovarian response was not influenced by the presence or absence of endometriosis." (PMID 30775688, 2018). "Correlation of serum AMH levels and the number of non-growing follicles in the biopsied cortical tissues in endometriosis and control subjects, including age, type of AMH kit, and the laboratory performing the analysis as covariates." (PMID 28791295, 2017). "However, the mechanisms responsible for reduced AMH levels in patients with endometriosis, particularly those without OMA, are not entirely clear." (PMID 40507534, 2025). "In addition, AMH levels in peritoneal fluid were positively correlated with serum AMH levels in both women with and without endometriosis." (PMID 40002761, 2025). "However, further investigations revealed that low AMH levels, even in severe endometriosis, did not affect oocyte quality or pregnancy outcome despite reducing oocyte numbers." (PMID 39493123, 2024). "However, in addition to the possible negative effect of endometriosis on ovarian reserve, serum AMH levels significantly decrease after laparoscopic cystectomy for endometrioma." (PMID 37370122, 2023). "Although some studies have not shown a correlation between AMH and endometriosis, other investigations have indicated that significantly lower AMH levels could be found in women with more severe forms of the disease." (PMID 36294778, 2022). "These previous reports may indicate that the endometrium and endometriotic tissue may be the target of AMH; however, the exact role of AMH in the growth and maintenance of endometriosis is not fully elucidated." (PMID 33263001, 2020). "Thus, unilateral endometriosis negatively affects ovarian reserve although not to statistical significance, while bilateral ovarian endometriomas result in significantly decreased AMH levels from an early age." (PMID 26596960, 2015).
endometriosis (continued). "However, as for patients with endometriosis in this study, the impacts of diagnosis of endometrioma and different operative procedures on serum AMH level were not significant." (PMID 26359251, 2015). "Moreover, sHLA-G was not related to embryoquality, pregnancy rates, AMH, age or endometriosis." (PMID 38381778, 2024). "However, the role of AMH in the functional regulations of endometriosis is not well understood." (PMID 33263001, 2020). "Inclusion: Patients who had not reached menopause, with or without extraovarian endometriosis including deep infiltrative endometriosis (DIE), underwent conservative surgery, and had AMH level test results before surgery, 2 weeks and 3 months postoperatively." (PMID 40922712, 2025). "Next, we evaluated AMH, KL, and GDF-9 protein expression in the ovaries of rats with and without endometriosis." (PMID 40002761, 2025). "Conversely, predictors of pregnancy achievement for endometriosis patients who were not treated before IVF were basal serum levels of FSH (p = 0.048) and AMH (p = 0.007), but not of P4 (0 = 0.524)." (PMID 36294778, 2022). "Conversely, another retrospective study did not identify preoperative AMH values to be predictive of conception (natural or through IVF) after surgery in patients with stage III and IV endometriosis, including cases operated on for colorectal endometriosis, with a mean age of 30 years." (PMID 40507534, 2025). "Similarly, a prospective cohort study did not identify a significant difference in the baseline AMH levels between those with SUP and endometriosis-free controls (p = 0.19)." (PMID 40507534, 2025).
hyperandrogenism (71 papers, 2010 to 2026). Excessive secretion of androgens from the adrenal glands or gonads. "The AMH is upregulated by androgen levels and has the ability to suppress aromatase activity, causing hyperandrogenism." (PMID 40564059, 2025). "No studies or analyses to date have specifically investigated the diagnostic accuracy of AMH in replacing hyperandrogenism for PCOS." (PMID 36900051, 2023). "Hyperandrogenism is also associated with high levels of Anti-Müllerian hormone (AMH) in women with PCOS." (PMID 36733795, 2022). "In PCOS women, elevated AMH concentrations are associated with hyperandrogenism and lower live birth rates." (PMID 32156287, 2020). "Follicular resistance to FSH signaling may be partly caused by intra-ovarian hyperandrogenism as well as elevated AMH levels." (PMID 40869727, 2025). "Another prevalent component that may be linked to PCOS and contribute to anovulation, hyperandrogenism, and a rise in AMH in this condition is hyperinsulinemia." (PMID 38549135, 2024). "Moreover, in PCOS, increased levels of circulating insulin contribute to hyperandrogenism, which causes a derangement in folliculogenesis, thereby contributing to polycystic ovary morphogenesis and higher than normal AMH." (PMID 38549135, 2024). "However, when both hyperandrogenism and anovulation are statistically confronted with excess serum AMH, the association is significant with the latter, whereas the former would simply be a confounding factor." (PMID 33013710, 2020). "However, our data suggested that FAI was more strongly predicted by BMI than by AMH, although women with both increased BMI and high follicle counts were most at risk of biochemical hyperandrogenism." (PMID 31616381, 2019). "Women with PCOS are known by increased serum AMH levels, which have been correlated to the disease severity, and to the all of its clinical diagnostic criteria including polycystic ovarian morphology, oligo/anovulation, and hyperandrogenism." (PMID 30288481, 2018). "By comparing the pattern of co-variation between AMH and Luteinizing Hormone, two compounds closely linked to hyperandrogenism and anovulation in PCOS, the involvement of the Hypothalamic-Pituitary-Ovarian axis in PCOS pathology could be elucidated." (PMID 24023708, 2013). "An application of AMH in pregnant mice induced neuroendocrine dysfunction with increased LH pulsatility and hyperandrogenism persisting in the exposed female’s offspring." (PMID 41515619, 2026). "In conclusion, AMH serum levels were positively correlated with hyperandrogenism and negatively with metabolic factors, although the connection between AMH and BMI has a more complex nature." (PMID 40564059, 2025). "Dysregulated AMH expression is a hallmark of polycystic ovary syndrome (PCOS), a common endocrine and metabolic disorder characterized by hyperandrogenism, anovulation, and polycystic ovarian morphology." (PMID 40257231, 2025). "Anti-Müllerian hormone (AMH), often elevated in PCOS, is linked to both androgen excess and insulin resistance." (PMID 41155582, 2025). "Of these studies, phlebotomy had androgenic profile benefits such as regulating hyperandrogenism and insulin resistance, whereas acupuncture modifies sex hormone levels, reduces weight, and lowers anti-Müllerian hormone (AMH)." (PMID 39479136, 2024). "Despite affecting fertility, PCOS is identified by elevated levels of AMH due to insulin actions in granulosa cells, which are marked by hyperandrogenism." (PMID 39336427, 2024). "In known PCOS patients, the combination of hyperandrogenism and AMH levels was found to have a high sensitivity and specificity for PCOS diagnosis." (PMID 38800769, 2024). "Prenatal AMH treatment in mice resulted in PCOS features in adulthood: hyperandrogenism, LH elevation, sporadic ovulation, and fertility defects." (PMID 36733795, 2022).
hyperandrogenism (continued). "Whilst this is a broad topic with other factors involved such as lipid metabolism, growth factors and cytokines, here we will focus on core hormonal factors linking endocrine and metabolic dysfunction - hyperinsulinemia, hyperandrogenism and AMH." (PMID 36733795, 2022). "In our study, women with high AMH level had greater prevalence of hyperandrogenism, PCOM, oligo/amenorrhea and PCOS, consistent with several earlier studies." (PMID 35236324, 2022). "Women with high AMH had greater prevalence of hyperandrogenism (HA), polycystic ovarian morphology (PCOM) and amenorrhea than women with low or average AMH." (PMID 35236324, 2022). "The present study demonstrated that all 3 PCOS diagnostic hallmarks, namely hyperandrogenism, PCOM, and oligo/amenorrhea, were associated with high AMH levels." (PMID 35236324, 2022). "The interrelationships between hyperinsulinemia, androgen excess, and AMH are potentially reflected in pregnancies complicated by hyperinsulinemic disorders." (PMID 36733795, 2022). "By comparing wild-type and pseudo germ-free mice, we found that gut microbiota depletion did not affect the occurrence of oestrous cycle disorders, serum AMH levels or ovarian morphological changes induced by DHEA but aggravated hyperandrogenism." (PMID 36619569, 2022). "These are helpful to rule out other conditions causing menstrual cycle irregularities and/or hyperandrogenism; and/or comorbidities associated with PCOS and include blood tests, pelvic ultrasound, anti-Müllerian hormone (AMH), and insulin resistance." (PMID 36010282, 2022). "In the present study, women were diagnosed according to the NIH criteria, i.e.hyperandrogenism, and anovulation, and indeed, AMH was correlated with circulating androgens." (PMID 36309748, 2022). "AGCT is rarely considered in the differential diagnosis of patients with elevated AMH levels; instead, patients with elevated AMH levels and hyperandrogenism are more likely to be diagnosed with polycystic ovarian syndrome (PCOS), which is much more common." (PMID 33828986, 2021). "The question of variation in AMH expression according to the PCOS phenotype is in fact very complex because principal component analysis has shown that the markers of hyperandrogenism and oligoanovulation are closely related." (PMID 33013710, 2020). "In this model, called PAMH, high AMH concentrations during gestation resulted in increased pulsatility of GnRH and LH, which was responsible for gestational hyperandrogenism." (PMID 33013710, 2020). "To summarize, AMH excess in GCs from PCO would be an indirect consequence of hyperandrogenism and would be involved in the follicle excess of PCO and in the follicular arrest in anovulatory patients." (PMID 33013710, 2020). "Studies concluded that obesity, insulin resistance, and hyperandrogenism play major roles in the increasing level of AMH." (PMID 29426356, 2018). "AMH value rise when hyperandrogenism is present therefore serum AMH levels also reflect the phenotype of PCOS." (PMID 25119192, 2014). "Menstrual history, clinical manifestations of hyperandrogenism, ovarian ultrasound assessments, and the levels of AMH, LH, FSH, and estradiol were collected." (PMID 25119192, 2014). "In adults, PCOS is diagnosed when at least two of the following three features are present: clinical or biochemical hyperandrogenism, ovulatory dysfunction, and polycystic ovarian morphology on ultrasound or elevated anti‐Müllerian hormone (AMH) levels, with exclusion of other etiologies." (PMID 41583231, 2025). "Hyperandrogenism in PCOS is compounded by elevated anti-Müllerian hormone (AMH) levels." (PMID 40013621, 2025). "The reverse may also occur, where women with phenotype B (menstrual irregularity and hyperandrogenism but with normal ovaries) may have elevations in AMH." (PMID 40868196, 2025).